PFN1 (profilin 1)
Diseases named in the same sentence as PFN1 in open-access papers (continued):
Sharing a sentence is not in itself a finding about the gene and the disease.
breast carcinoma (continued). "Taken together, these observations suggest for the first time that Pfn1 is a negative regulator of mammary carcinoma aggressiveness." (PMID 17940506, 2007). "Since these cellular changes are precursor to tumour cell dissemination in vivo, our findings for the first time provide a possible insight on why Pfn1 expression has to be downregulated in breast cancer cells." (PMID 17940506, 2007). "We show that loss of Pfn1 expression leads to enhanced motility and matrigel invasiveness of MDA-MB-231 breast cancer cells." (PMID 17940506, 2007). "Taken together, these data demonstrate that Pfn1 overexpression suppresses orthotopic tumorigenicity and micro-metastasis of breast cancer cells." (PMID 17940506, 2007). "Third, the present study is the first demonstration of the in vivo effect of Pfn1 overexpression on breast cancer cells in an orthotopic setting." (PMID 17940506, 2007). "Taken together, these data demonstrate that loss of Pfn1 expression primes HMEC and breast cancer cells to a more migratory phenotype, and thus support our overall postulate." (PMID 17940506, 2007). "To address this question, in this study we evaluated how perturbing Pfn1 affects motility and invasion of breast cancer cells." (PMID 17940506, 2007). "Our data rather suggest that actin binding is necessary for Pfn1-induced suppression of breast cancer cell motility." (PMID 17940506, 2007). "In the present study, we evaluate for the first time how perturbing Pfn1 affects the motility and invasiveness of breast cancer cells as well as their normal counterparts." (PMID 17940506, 2007). "In vivo effect of Pfn1 overexpression on mammary tumour cells has been examined for only one cell line (CAL51) so far where suppression of tumorigenicity was observed." (PMID 17940506, 2007). "A previous study also reported that Pfn1 binds to PTEN (an antagonist of PI3K signaling) and that Pfn1’s interaction protects PTEN from ubiquitination, leading to an increased cellular abundance of PTEN in MDA-231 breast cancer cells when Pfn1 is stably overexpressed." (PMID 38141770, 2024). "PFN1 has also been characterized as a tumor-suppressor in human breast cancer." (PMID 33804610, 2021). "We can hypothesize that some downstream regulation is at play, which leads to decreased PFN1 protein levels in breast cancer cells despite rather uniform expression of the gene." (PMID 34681026, 2021). "PFN1 has been viewed as a negative regulator for the migration and invasion of breast cancer cells." (PMID 27188458, 2016). "We hypothesized that phosphorylation of profilin 1 at S137 could be crucial in breast cancer progression." (PMID 25084196, 2014). "In addition, a tumor-suppressive action of Pfn1 on breast cancer cell lines was reported, with a novel finding that Pfn1 overexpression was associated with a dramatic upregulation of p27 levels." (PMID 25103363, 2014). "Whether phosphorylation of profilin 1 affects migration and invasion of breast cancer cells expressing various profilin 1 mutants was next assessed by wound healing assays and boyden chamber assays respectively." (PMID 25084196, 2014). "Previous studies from our laboratory have shown that genetically modulating Pfn-1 expression significantly impacts proliferation, migration, and invasion of breast cancer cells in vitro, and mammary tumor growth, dissemination, and metastatic colonization in vivo." (PMID 24520372, 2014). "Pfn-1 modulates breast cancer aggressiveness, and genetic overexpression of Pfn-1 reduces tumor formation in vivo, and reduces cell migration and invasion in breast cancer cells." (PMID 24520372, 2014).
breast carcinoma (continued). "It would be interesting to demonstrate the importance of nuclear profilin and nuclear phosphoprofilin in breast cancer progression and targeting profilin 1 phosphorylation for cancer therapy could be a prudent option." (PMID 25084196, 2014). "Although further mechanistic studies are needed to elucidate why Pfn1 depletion increases motility in breast cancer cells, yet dramatically inhibits motility of other cell types, such as vascular endothelial cells, certain speculations may be appropriate." (PMID 17940506, 2007). "We postulated that Pfn1 is a negative regulator of mammary carcinoma aggressiveness." (PMID 17940506, 2007). "Finally, we evaluated the effect of Pfn1 overexpression on breast cancer cells in vivo in an orthotopic xenograft model system." (PMID 17940506, 2007). "Conversely, overexpression of Pfn1 suppresses motility and invasiveness of breast cancer cells." (PMID 17940506, 2007). "To better relate to the process of tumour cell invasion in vivo, we next investigated whether perturbing Pfn1 expression modulates the intrinsic invasiveness of breast cancer cells." (PMID 17940506, 2007). "If true, perturbing Pfn1 could prove to be a good molecular strategy for limiting aggressiveness of breast cancer cells." (PMID 17940506, 2007). "Profilin 1 protein can suppress tumorigenicity in breast cancer cells." (PMID 15784140, 2005). "In addition, both PFN1 overexpression and downregulation in breast cancer cells decrease the numbers and size of sphere formed in anchorage-independent culture and the loss of PFN1 showed negative effects on tumor-initiating ability with cancer stemness associated transcriptome alteration." (PMID 33590416, 2021). "The overexpression of PFN1 could negatively regulate cancer cell motility in breast cancer cells." (PMID 34681026, 2021). "By quantifying the tract lengths of dual-colored fibers, we found that PFN1 knockdown significantly decreased DNA replication speed in multiple human cell lines including MCF-10A, HEK293T, HeLa and breast cancer MCF-7 and MDA-MB-231." (PMID 36319634, 2022). "For example, although both PFN1 and PFN2 are expressed in breast cancer cells, they have distinct effects on cell migration and invasion ability." (PMID 33590416, 2021). "To determine the effect of Ser71 phosphorylation, we virally expressed untagged wild type Pfn1 and its S71A or S71D mutants in the MDA-MB-231 breast cancer cells at levels 2–3-folds over endogenous Pfn1." (PMID 34235154, 2021). "Based on the results of the present study, we suggest the use of HSP90AB1, DAD1, PFN1 and PUM1 in any combination of threes (triplet) for normalization of the expression of genes of interest in SK-BR-3 breast cancer cell line." (PMID 34681026, 2021). "As predicted, treatment with each of these proteins, except for Profilin 1, downregulated Snail in TMD breast cancer cells and 4T1 mammary tumor cells." (PMID 32128277, 2020). "Pfn-1 is also dephosphorylated on Ser137 by PP1 and overexpression of Pfn-1 phosphonull mutant showed decreased migration, growth, and invasion on tumorigenesis in breast cancer cells, showing the promoting effect of Pfn Ser137 phosphorylation." (PMID 38999976, 2024). "Applying label-free proteomic quantitation method and statistical analysis, several differentially expressed proteins (DEPs) were identified in the serum of breast cancer patients compared to controls, including SBSN, ANG, PCOLCE, and WFDC3 (upregulated), and PFN1, FLNA, and DSG2 (downregulated)." (PMID 39990193, 2024). "In breast cancer, CHIP promotes the MDA-MB231 cell migration through down-regulating Pfn1." (PMID 29921293, 2018).
breast carcinoma (continued). "However, a recent report highlighted the opposite roles of PFN1 and PFN2 in the membrane protrusion, cell migration and invasion of breast cancer cells." (PMID 27188458, 2016). "We found PKC elevated in the breast cancer samples and another study found increased PI3K levels in breast cancers indicating that profilin 1 phosphorylation could be an obligatory signaling event in promoting breast tumorigenesis." (PMID 25084196, 2014). "In the present study, we report elevated profilin 1 expression in non-metastatic, primary breast carcinoma tissues from Indian population." (PMID 25084196, 2014). "To test this hypothesis, we adopted gene-silencing approach where we transiently transfected MDA-MB-231 breast cancer cells and HMEC with either a control or Pfn1-specific siRNA, and examined the changes in cell motility." (PMID 17940506, 2007). "Because of a general theme of Pfn1 downregulation in many different breast cancer cell lines, we specifically hypothesised that downregulation of Pfn1 expression confers increasing aggressiveness to both normal HMEC and breast cancer cells." (PMID 17940506, 2007). "Pfn1-overexpressing CAL51 breast cancer cells failed to form tumours when xenografted subcutaneously in nude mice, which suggested that Pfn1 could also be a tumour-suppressor protein." (PMID 17940506, 2007). "Similar to previous observation of Pfn1 downregulation in human breast cancer tissue and a wide range of other breast carcinoma cell lines, we observed that MDA-MB-231, our model breast cancer cell line, also expresses significantly less Pfn1 compared to normal HMEC." (PMID 17940506, 2007).
atherosclerosis (8 papers, 2010 to 2024). A disease characterized by the build-up of fatty material and calcium deposition in the arterial wall resulting in partial or complete occlusion of the arterial lumen. "Although there are no currently known human diseases with loss of vascular endothelial Pfn1 expression, Pfn1 expression is elevated in vascular EC (EC) in atherosclerosis, diabetes, and clear cell renal cell carcinoma." (PMID 37781098, 2023). "The over-expression of profilin-1 is associated with atherosclerosis and other cardiovascular complications." (PMID 34867370, 2021). "The quality of PFN1-CD-MNP as a diagnostic agent imaging atherosclerosis was tested using the ApoE-deficient atherosclerotic mouse model." (PMID 32106607, 2020). "Our further studies revealed that the vascular expression and serum levels of profilin-1 are associated with atherosclerosis in vivo." (PMID 21049052, 2010). "We found that profilin levels were significantly elevated in patients with the most severe aortic atherosclerosis score, indicating that profilin-1 serum levels were associated with the degree of atherosclerosis in humans." (PMID 21049052, 2010). "Importantly, we also assessed whether the serum levels of profilin-1 were associated with the degree of atherosclerosis in humans." (PMID 21049052, 2010). "Recently, profilin-1 emerged as a new player in the field of atherosclerosis; it is accumulated in high concentrations in stable atherosclerotic plaques and thrombi from infarct-related arteries in cases of acute myocardial infarction." (PMID 38652420, 2024). "In the context of these data, it is interesting to note that in atherosclerosis setting, global heterozygous deletion of the Pfn1 gene reduces inflammation and macrophage activity conferring partial protection from the severity of atherosclerosis." (PMID 37781098, 2023). "Another protein molecule for atherosclerosis targeting is profilin-1, which is an actin binding protein." (PMID 34867370, 2021). "Profilin-1 is an intracellular actin-binding protein involved in cytoskeletal dynamics that has also been observed to be highly expressed in human atherosclerosis and to exert direct atherogenic effects on VSCMs." (PMID 32106607, 2020). "PFN1 expression is significantly enhanced in human atherosclerotic plaques and the serum levels of PFN1 correlate with the degree of atherosclerosis in humans." (PMID 30235220, 2018). "There was a clear trend towards increased levels of profilin-1 expression in animals that received high fat diet and subsequently developed atherosclerosis." (PMID 21049052, 2010). "More recently, we specified the importance of profilin-1 for atherogenesis in vivo, as profilin-1 heterozygosity conferred protection from atherosclerosis in LDL receptor-null mice." (PMID 21049052, 2010). "Another ECM molecule that is overexpressed in atherosclerosis and could be targeted is the actin-binding protein (profilin-1)." (PMID 39204382, 2024). "Profilin-1 may therefore represent an important novel target for therapeutic and preventive strategies against atherosclerosis." (PMID 21049052, 2010). "Furthermore, the correlation between profilin-1 serum levels and the degree of atherosclerosis was assessed in humans." (PMID 21049052, 2010). "Together with our previous reports, these data suggest that profilin-1 may play a role in early and advanced stages of atherosclerosis." (PMID 21049052, 2010). "Profilin-1 expression is significantly enhanced in human atherosclerotic plaques compared to the normal vessel wall, and the serum levels of profilin-1 correlate with the degree of atherosclerosis in humans." (PMID 21049052, 2010).
atherosclerosis (continued). "The in vivo knockdown of this upregulated protein using profilin-1 siRNA-loaded into inorganic NPs (i.e., gold NPs) was demonstrated to reduce the proliferation and migration of smooth muscle cells and improve the therapeutic efficiency in the atherosclerosis model." (PMID 39204382, 2024). "We recently demonstrated that profilin-1 overexpression triggers indicators of endothelial dysfunction downstream of LDL signaling, and that attenuated expression of profilin-1 confers protection from atherosclerosis in vivo." (PMID 21049052, 2010). "Finally, we found that profilin-1 serum levels were significantly elevated in patients with severe atherosclerosis in humans (p<0.001 vs. no atherosclerosis or control group)." (PMID 21049052, 2010).
bladder cancer (8 papers, 2014 to 2025). "In metastatic bladder cancer cells, PFN1 facilitates integrin-mediated activation of the Wnt/Ca2+ pathway via PIP2, promoting fibronectin adhesion, actin remodeling, and cell motility." (PMID 40981267, 2025). "Downregulation of Pfn1 has been previously reported in breast, hepatic, pancreatic, and bladder cancer, in which it contributes to the malignant progression of tumor cells." (PMID 25103363, 2014). "Recent studies report that profilin 1 is a potential biomarker for bladder cancer aggressiveness and suppressing its expression in T24 bladder cancer cell line decreased their motility with a concomitant decrease in actin polymerization." (PMID 25084196, 2014). "Additionally, PFN1 has been observed to be overexpressed in renal cell carcinoma and proposed as a urine biomarker for bladder cancer aggressiveness." (PMID 35422813, 2022). "In the context of bladder cancer, PFN1 has been identified as a critical regulator of non-canonical Wnt/Ca2+ signaling." (PMID 40981267, 2025).
diabetes (8 papers, 2010 to 2025). "Dysregulation of profilin 1 level in the serum is associated with diabetes and implicated in cancer and cardiovascular diseases." (PMID 36366577, 2022). "Taken together, these findings set the stage for a prominent role of profilin-1 as a modulator of the actin cytoskeleton, which may underlie the pathology of vascular diseases, including diabetes." (PMID 24090212, 2013). "At six months of diabetes the amount of Diaph1 as well as PFN1 was decreased and the relative amount of CML-AGE was elevated when compared to control mice (P ≤ 0.01, P ≤ 0.01, P ≤ 0.05, respectively)." (PMID 37462767, 2023). "Consistent with the qRT-PCR results for the liver, Sardh and Pfn1 showed a higher expression level in gerbils with diabetes." (PMID 29394254, 2018). "Under pathological conditions, such as diabetes or atherosclerosis (AS), profilin-1 levels were increased in atherosclerotic lesions, the aorta or in serum." (PMID 24090212, 2013). "Under pathological conditions such as diabetes, profilin-1 levels are increased in the vascular endothelium." (PMID 21049052, 2010). "Our previous work demonstrated that profilin-1 is present on the luminal surface of the endothelium in human and experimental diabetes, and that increased profilin-1 levels triggered various indicators of endothelial dysfunction." (PMID 21049052, 2010). "Because endothelial damage stimulated by profilin-1 in diabetes is surprisingly similar with that in lipid oxidation, it is conceivable that profilin-1 may function in a common pathway that induces vascular endothelial injuries in vascular lesions." (PMID 24090212, 2013). "Therefore, our finding that the expression levels of Sardh and Pfn1 were significantly higher in the livers of animals in gerbils with diabetes than those in the control animals indicates that these genes are associated with diabetes, particularly at the expression level." (PMID 29394254, 2018). "In summary, PFN-1 may serve as a novel regulator that mediates the effects of AGEs-activated RhoA/ROCK signaling pathway on the redistribution of actin cytoskeleton, and inhibition of PFN-1 expression can protect against cardiomyocytes injury and cardiac dysfunction in diabetes." (PMID 29238726, 2017).
cardiac hypertrophy (7 papers, 2016 to 2026). "Among the various actin-binding proteins (ABPs) associated with cardiac hypertrophy we found as overexpressed the protein profilin-1 that accelerates actin aggregation and increase the development of cardiac hypertrophy." (PMID 38312589, 2024). "Increased expression of profilin-1 in vascular smooth muscle cells induces stress fiber formation and causes cardiac hypertrophy and fibrosis by modulating actin polymerization." (PMID 36458175, 2022). "The inhibition of profilin-1 expression in H9c2 cells and Sprague–Dawley rats can attenuate cardiac hypertrophy induced by AEGs." (PMID 36428995, 2022). "Previous studies found that elevated PFN-1 expression contributed to pathological cardiac hypertrophy and fibrosis by increasing actin polymerization in spontaneously hypertensive rats (SHRs)." (PMID 29238726, 2017). "Global knockdown of profilin-1 in SHRs attenuated cardiac hypertrophy, while overexpression promoted it." (PMID 26956799, 2016). "Several studies have suggested PFN1 to be a critical promoter of cardiac hypertrophy." (PMID 30235220, 2018). "Previous studies indicated that PFN-1, an important actin-binding protein, could play an important role in pathological cardiac hypertrophy and activating hypertrophic signaling cascade." (PMID 29238726, 2017). "Restoration of FBXL4 expression via AAV9 delivery ameliorated cardiac hypertrophy and dysfunction in FBXL4-iCKO mice, while AAV9-mediated PFN1 knockdown or pharmacological inhibition partially reversed these phenotypes." (PMID 41589689, 2026). "Overexpression of profilin-1 in the vascular tissues of FVB/N mice leads to vascular remodeling and hypertension by increasing actin aggregation, which provides mechanical stress for the development of cardiac hypertrophy." (PMID 36428995, 2022). "Consistent with elevated PFN-1 expression in hypertrophic heart, downregulation of PFN-1 attenuated cardiac hypertrophy while PFN-1 overexpression or PFN-1 transgene promoted vascular and cardiac hypertrophy in SHRs." (PMID 29238726, 2017). "In our previous study, we found that PFN-1 plays an important role in AGEs-induced endothelial abnormalities via promoting cytoskeleton rearrangement and redistribution and silencing the expression of PFN-1 attenuated AGEs-induced myocardium injury including cardiac hypertrophy and fibrosis in vivo." (PMID 29238726, 2017).